MDC1 (mediator of DNA damage checkpoint 1)
Diseases named in the same sentence as MDC1 in open-access papers (continued):
Sharing a sentence is not in itself a finding about the gene and the disease.
ataxia telangiectasia (2 papers, 2020 to 2024). Ataxia-telangiectasia is the association of severe combined immunodeficiency (affecting mainly the humoral immune response) with progressive cerebellar ataxia. "The increase in γ-H2AX phosphorylated at Ser139 by protein kinase ATM (mutated in ataxia-telangiectasia) leads to the recruitment of the mediator of DNA damage checkpoint protein 1 (MDC1) as a response to the formation of double strand breaks (DSB)." (PMID 32357578, 2020).
colon carcinoma (2 papers, 2012 to 2025). "The activation of a transient intra-S-phase checkpoint is characterized by limited availability of p-NBS1Ser343 in cell extracts and limited binding of NBS1 to chromatin via MDC1 during the critical phase at which colon carcinoma cells accumulate in early S-phase and attempt to repair damaged DNA." (PMID 23097684, 2012).
colorectal cancer (2 papers, 2022 to 2023). A primary or metastatic malignant neoplasm that affects the colon or rectum. "ID3 and PPARγ influence the radiosensitivity of colorectal cancer cells by interacting with MDC1 to form a positive feedback loop that promotes DNA damage repair." (PMID 37170184, 2023). "Meanwhile, immunofluorescence also showed that ID3, MDC1, and γH2AX foci were increased in colorectal cancer cells after irradiation." (PMID 37170184, 2023). "We found that when colorectal cancer cells were exposed to irradiation, ID3, γH2AX, and MDC1 increased and formed foci to repair DNA damage caused by irradiation." (PMID 37170184, 2023). "To clarify the specific mechanism of ID3 in reducing the radiosensitivity of colorectal cancer cells, we detected the expression of ID3 and DNA damage repair proteins MDC1 and γH2AX after irradiation by western blotting." (PMID 37170184, 2023). "In conclusion, through communication with MDC1, ID3 and PPARγ formed a positive feedback loop to promote the repair of DNA damage, thus affecting the radiosensitivity of colorectal cancer cells." (PMID 37170184, 2023). "Next, we analyzed whether the regulation of miR-22-3p and MDC1 by AP4 is conserved in adenomas from ApcMin/+ mice, which represent a model for inherited colorectal cancer (familial adenomatous polyposis (FAP)." (PMID 35624466, 2022).
gastric cancer (2 papers, 2022 to 2025). A primary or metastatic malignant neoplasm involving the stomach. "Similarly, MDC1 deficiency correlated with diffuse subtype and higher-grade tumors, indicating that its loss may also contribute to aggressive gastric cancer phenotypes." (PMID 40869030, 2025).
leukemia (2 papers, 2014 to 2025). A malignant (clonal) hematologic disorder, involving hematopoietic stem cells and characterized by the presence of primitive or atypical myeloid or lymphoid cells in the bone marrow and the blood. "It remains to be determined whether and to what extent the DC content of our TCR-αβ/CD19-depleted HSC grafts and, in particular, the remarkably high numbers of MDC1, MDC2 and plasmacytoid DCs infused correlate with infection control, GVHD and/or leukemia recurrence." (PMID 25179788, 2014).
adenoma (1 paper, 2022). A neoplasm arising from the epithelium. "Furthermore, a decrease in Mdc1 mRNA expression was found in adenomas from ApcMin/+ mice with intestinal epithelial cell (IEC)-specific deletion of Ap4 when compared to Ap4-wild-type ApcMin/+ mice." (PMID 35624466, 2022). "In addition, a decrease in Mdc1 protein expression and in the number of Mdc1-positive cells was detected by immunohistochemistry in Ap4∆IEC adenomas of 120 days old ApcMin/+ mice when compared to Ap4fl/fl adenomas." (PMID 35624466, 2022).
anemia (1 paper, 2022). A reduction in the number of red blood cells, the amount of hemoglobin, and/or the volume of packed red blood cells. "Among these genes, Fanconi anemia Complementation Group M (FANCM) and Mediator of DNA damage checkpoint protein 1 (MDC1) may be related to CSR due to their known roles facilitating a DNA damage response leading to DNA repair." (PMID 34628594, 2022).
Autoimmunity (1 paper, 2024). The occurrence of an immune reaction against the organism's own cells or tissues. "MDC1 is within the major histocompatibility complex (MHC) region in chromosome 6, a region known to be important in immune regulation containing many genetic variants associated with autoimmunity, including AITD." (PMID 37962983, 2024).
bladder cancer (1 paper, 2016). "Collectively, these results indicated that in RNF8-silenced bladder cancer cells, γ-H2AX and MDC1, which function upstream of RNF8, clearly formed IRIF after radiotherapy." (PMID 26788910, 2016).
breast and ovarian cancer (1 paper, 2014).
cardiomyopathy (1 paper, 2024). A disease of the heart muscle or myocardium proper. "The acceleration of the cardiomyopathy is coincident with the efficient displacement of utrophin by 2 of the microdystrophins (MDC1 and MDC4)." (PMID 38713520, 2024). "In agreement with their profound effect on survival, MDC1 and MDC4 induce severe cardiomyopathy with features of DCM." (PMID 38713520, 2024). "We present the data and observations in support of the first mechanism (utrophin displacement) as the main contributor to microdystrophin-induced acceleration of cardiomyopathy and to overload of the UPS occurring if the expression levels are high enough (as with MDC1)." (PMID 38713520, 2024).
colorectal adenocarcinoma (1 paper, 2022). The most common type of colorectal carcinoma. "To determine whether the regulation of MIR22HG/miR-22-3p and MDC1 by AP4 also occurs in primary CRCs, we analyzed the expression of these genes in 15 cohorts of colorectal adenocarcinomas (COAD) provided by the TCGA consortium and GEO." (PMID 35624466, 2022).
Fanconi anemia (1 paper, 2021). Fanconi anemia (FA) is a hereditary DNA repair disorder characterized by progressive pancytopenia with bone marrow failure, variable congenital malformations and predisposition to develop hematological or solid tumors. "BRIP1 and FANCC belong to the Fanconi anemia pathway while MDC1 and TP53BP1 are conserved DNA damage response genes." (PMID 34220964, 2021).
hepatocellular carcinoma (1 paper, 2024). A malignant tumor that arises from hepatocytes. "FAD induces caspase-dependent apoptosis through an increase in BAX and cleaved caspase-3 and a decrease in BCL2, RAB51, BRCA1, and MDC1 in hepatocellular carcinoma." (PMID 39765861, 2024).
hypothalamic tumours (1 paper, 2022). "In our young cohort, its presence was associated with more MDC1 disease (50%) and few (15%) hypothalamic tumours, in line with previous reports, which most likely accounts for these neuroendocrine outcomes." (PMID 35159015, 2022).
Immunodeficiency (1 paper, 2017). Failure of the immune system to protect the body adequately from infection, due to the absence or insufficiency of some component process or substance. "Similarly, MDC1‐deficient mice also suffer from immunodeficiency and display moderately decreased levels of class‐switch recombination, consistent with the NHEJ defect we observe in our assays." (PMID 28275011, 2017).
Infertility (1 paper, 2025). "In the non-ART sample, we identified genome-wide significant fetal effects on fetal survival for SNPs within regions harboring genes relevant to infertility and fetal development, such as MDC1, MICB, HCP5, and NOTCH4." (PMID 41325449, 2025).
Insulin resistance (1 paper, 2022). Increased resistance towards insulin, that is, diminished effectiveness of insulin in reducing blood glucose levels. "Interactome analysis using the cancer-related phosphoproteome of palmitate-induced insulin resistance revealed that several proteins interacted with each other, and mediator of DNA damage checkpoint protein 1 (MDC1) was the central protein in cancer signal transduction." (PMID 35055191, 2022).
liver cancer (1 paper, 2017). An epithelial or non-epithelial malignant neoplasm that arises from the liver. "and cancer driver genes (ATRX, MDC1, RIF1, APC and PCM1) showed a phosphorylation related signal transition network affecting cell proliferation ability and revealed the extreme complex nature of phosphoproteome transformation in liver cancer cells." (PMID 28883432, 2017).
lobular breast cancer (1 paper, 2022). "High levels of circulating MDC1, however, associated with primary tumor histological subtype (higher prevalence of lobular breast cancer, p = 0.007), whereas low levels of MDC1 correlated with visceral metastases (p = 0.038)." (PMID 35626676, 2022).
lung adenocarcinoma (1 paper, 2021). A carcinoma that arises from the lung and is characterized by the presence of malignant glandular epithelial cells. "In the analysis of radiation-induced apoptosis in A549 cells, which are human lung adenocarcinoma-derived epithelial-like cells, apoptosis was largely suppressed with MDC1 small interfering RNA, which was restored with addition of MDC141." (PMID 34321534, 2021).
melanoma (1 paper, 2025). A malignant, usually aggressive tumor composed of atypical, neoplastic melanocytes. "Our previous work uncovered a novel role for αSyn in the recruitment of 53BP1 to ribosomal DNA DSBs, downstream of γH2AX signaling and upstream of MDC1 activity, in the SK-Mel28 melanoma cell line." (PMID 40182046, 2025).
Miscarriage (1 paper, 2019). A pregnancy that ends at a stage in which the fetus is incapable of surviving on its own, defined as the spontaneous loss of a fetus before the 22th week of pregnancy. "Our own findings support this idea, as we were able to demonstrate a significant lower number of mature MDC1 in miscarriage patients compared to normal pregnant women." (PMID 31681319, 2019). "Moreover, frequencies of HLA-DR-expressing MDC1 were reduced in miscarriage patients when compared to normal pregnant women." (PMID 31681319, 2019). "Moreover, miscarriage was characterized by lower Treg and MDC1 frequencies suggesting an interrelation between these two cell populations." (PMID 31681319, 2019). "Based on our findings, showing altered frequencies of total and mature MDC1 and MDC2 in miscarriage patients, we were curious whether both myeloid subsets would also possess a disturbed cytokine secretion profile." (PMID 31681319, 2019). "MDC1 from miscarriage patients had a significant reduced capacity to secrete IL-1β, IL-6, IL-10, and TNF, while MDC2 from miscarriage patients did not behave differentially from MDC2 of normal pregnant women." (PMID 31681319, 2019).
neuroblastoma (1 paper, 2023). Neuroblastoma (NB) is the most common solid, extracranial childhood tumor.
oral squamous cell carcinoma (1 paper, 2020). "In oral squamous cell carcinoma, this method was used for the CD44, CD73, and mediator of DNA damage checkpoint protein 1 (MDC1 protein) evaluation." (PMID 33287350, 2020).
serous ovarian cancer (1 paper, 2026). "Moreover, shRNA-mediated depletion of MDC1 resulted in olaparib resistance in the human high-grade serous ovarian cancer cell line PEO1, that carries the BRCA2 c.5193C>G mutation leading to a complete loss of protein stability." (PMID 41408464, 2026).
Telangiectasia (1 paper, 2013). Telangiectasias refer to small dilated blood vessels located near the surface of the skin or mucous membranes, measuring between 0.5 and 1 millimeter in diameter. "Ataxia telangiectasia mutated was activated but not its 53BP1 and MDC1 targets." (PMID 24021630, 2013).
teratozoospermia (1 paper, 2021). "Finally, we identified two heterozygous nonsense variants (c.472C>T; p.(Gln158*) in Exon 3 and c.2134C>T; p.(Gln712*) in Exon 7) in Mediator of DNA Damage Checkpoint 1 (MDC1) in patient AUS11, who suffered from mild oligozoospermia combined with astheno-teratozoospermia." (PMID 34089056, 2021).
cancer (38 papers, 2007 to 2026). A tumor composed of atypical neoplastic, often pleomorphic cells that invade other tissues. "Collectively, these results suggest that RNF8 physically binds to and protects ATM-phosphorylated MDC1 from caspase-dependent proteolytic cleavage in BIN1-deficient cancer cells." (PMID 34948122, 2021). "As predicted, PARP1, one of the most representative cellular substrates of caspase-3 during apoptosis, was cleaved when si-MDC1 was transfected in BIN1-deficient cancer cells in the presence of cisplatin." (PMID 34948122, 2021). "We also observed that the cisplatin sensitivity restored by si-MDC1 in BIN1-deficient cancer cells was compromised by carbobenzoxy-valyl-alanyl-aspartyl fluoromethyl ketone (z-VAD-fmk) (20 μM), a cell-permeable pan-caspase inhibitor." (PMID 34948122, 2021). "Mice deficient for Mdc1, Rnf8, 53bp1 or Brca1 have increased cancer susceptibility likely due to their elevated levels of genomic instability." (PMID 21552324, 2011). "Additionally, the MDC1-depleted PEO1 cells showed slower fork speed confirming the phenotype in a BRCA-mutated human cancer line." (PMID 41408464, 2026). "Notably, loss of MDC1 impairs DNA repair, compromises genome integrity and enhances cancer susceptibility in mice." (PMID 28637007, 2017). "EBV and radiosensitivity are two high risk factors of human cancer, therefore, these genetic variants of MDC1 may also affect the susceptibility of cancer." (PMID 25198518, 2014). "This is further supported by the finding of the group of Sharon Cantor and our data presented here, confirming the PARPi resistance when MDC1 was depleted in human MDA-MB-436 (BRCA1-mutated) and PEO1 (BRCA2-mutated) cancer cells." (PMID 41408464, 2026). "Genomic alterations of MDC1 in human cancers have been shown to increase sensitivity to DNA damaging chemotherapeutic reagents including doxorubicin and cisplatin." (PMID 37079639, 2023). "Through JMJD1C binding to RNF8 and MDC1 demethylation at the Lys45 location, MDC1 increases the sensitivity of cancer cells to IR." (PMID 37808268, 2023). "For this purpose, RNF8 siRNA (si-RNF8) was transfected alone or co-transfected with si-MDC1 in BIN1-depleted cancer cells in the presence of cisplatin (2.0 μg/mL) for 72 h." (PMID 34948122, 2021). "MDC1 silencing in combination with radiation or chemotherapeutic agents presents a rational strategy for the treatment of ATM proficient cancers, which primarily depend on the ATM-Chk2 pathway activation for the repair of double strand DNA breaks." (PMID 32160908, 2020). "For instance, the human demethylase JMJD1C was stabilized by interaction with RNF8 and recruitment of RAP80-BRCA1, and MDC1 was demethylated at Lys45 through JMJD1C binding to RNF8 and MDC1, promoting cancer cell sensitivity to IR153." (PMID 32355263, 2020). "mDC1 are essential in presenting cancer-related antigens and inducing a Th1-fashioned immune response by producing high amounts of interleukin-12." (PMID 30635636, 2019). "We also identified alterations in genes involved in various critical biological processes: MDC1, associated with DNA damage response and drug resistance in MM; DAXX, involved in chromatin regulation; GPNMB, linked to immunosuppression in cancer; and XK, which plays a role in hematopoiesis." (PMID 39769182, 2024).